PUS3 (pseudouridine synthase 3)
Description:
Formation of pseudouridine at position 39 in the anticodon stem and loop of transfer RNAs.
Synonyms: FKSG32; DEG1; 2610020J05Rik; MRT55; NEDMIGS
Tractability: PROTAC: ubiquitination databases record sites on it.
Gene: Protein-coding gene on chromosome 11 (125,893,485 to 125,903,224, reverse strand). Ensembl gene ENSG00000110060.
Subcellular location: Nucleus
Subcellular location (Human Protein Atlas): Nucleoplasm; Cytosol
Pathways (Reactome):
Metabolism of RNA: tRNA modification in the nucleus and cytosol
Gene Ontology:
Molecular function: pseudouridine synthase activity; tRNA pseudouridine(38/39) synthase activity; tRNA pseudouridine synthase activity; RNA binding
Biological process: tRNA pseudouridine synthesis; mRNA pseudouridine synthesis; tRNA modification; pseudouridine synthesis; RNA modification
Cellular component: cytoplasm; cytosol; nucleus
Genetic constraint (gnomAD): Loss-of-function variants: 36 observed, 44.95 expected, observed/expected ratio (o/e) 0.8, 90% interval 0.61 to 1.06. The upper end of that interval is the gene's LOEUF score, 1.06, which puts it in group 4 of 6, group 1 being the genes least tolerant of losing a copy. Missense variants: 544 observed, 619.58 expected, observed/expected ratio (o/e) 0.88, 90% interval 0.82 to 0.94. Synonymous variants: 183 observed, 212.1 expected, observed/expected ratio (o/e) 0.86, 90% interval 0.76 to 0.98.
Homologues: Orthologues: chimpanzee PUS3 (99% identical), macaque PUS3 (97% identical), dog PUS3 (88% identical), rabbit PUS3 (87% identical), pig PUS3 (87% identical), mouse Pus3 (85% identical), guinea pig PUS3 (84% identical), rat Pus3 (84% identical), tropical clawed frog pus3 (54% identical), zebrafish pus3 (49% identical), Drosophila melanogaster CG3045 (39% identical), Caenorhabditis elegans tag-124 (28% identical). Paralogues in human: PUS1 (20% identical), PUSL1 (15% identical).
Diseases named in the same sentence as PUS3 in open-access papers:
PUS3 is named in the same sentence as 27 diseases in open-access papers, as found by Europe PMC text mining. Sharing a sentence is not in itself a finding about the gene and the disease. The quoted sentences say what the papers report.
Intellectual disability (9 papers, 2017 to 2025). "In humans, mutations in PUS3 protein were shown to reduce PUS3-dependent Ψ levels which cause intellectual disability." (PMID 40351534, 2025). "PUS3 primarily targets the 38 and 39 uridine residues in the tRNA anticodon loop; defects in PUS3 not only reduce Ψ levels but also associated with mental retardation." (PMID 41446042, 2025). "In humans, homozygous inactivating mutations in the PUS3 gene are linked to developmental delays, intellectual disability, and reduced lifespan due to decreased Ψ levels in tRNA." (PMID 39061374, 2024). "Recent findings have associated novel homozygous truncating mutations in PUS3 with intellectual disability, demonstrating the crucial role of pseudouridylation in cognitive development." (PMID 39061374, 2024). "There are several additional Ψ synthases responsible for pseudouridylation at other tRNA positions, and defects in some of these enzymes (including the Deg1 orthologue Pus3) are linked to neurodegenerative diseases such as intellectual disability in humans." (PMID 34445460, 2021). "In humans, homozygous mutation of the DEG1 orthologue PUS3 is correlated with intellectual disability, suggesting a significant contribution to tRNA functioning not only in yeast but also in humans." (PMID 28134782, 2017). "Mutations in the PUS3 gene have been associated with intellectual disability." (PMID 37701433, 2023). "Another tRNA modification recently linked to human neuropathies is Deg1/Pus3 dependent formation of pseudouridine (Ψ38/39), since homozygous DEG1/PUS3 mutations are linked to a severe form of intellectual disability, a syndrome which can also be caused by human Elongator defects." (PMID 30360492, 2018). "Furthermore, observations of Pus3 mRNA expression in the nervous system of mouse embryos indicates a possible role for it in neuronal development, which is corroborated by a report linking PUS3 truncation to intellectual disability in human." (PMID 34769301, 2021). "In S. cerevisiae the lack of Ψ38–39 causes temperature sensitivity, and even in human a correlation between homozygotic mutation causing expression of a non-functional Pus3 enzyme (pseudouridylates tRNA positions 38–39) and intellectual disabilities was found." (PMID 33374637, 2020).
viral infection (4 papers, 2020 to 2024). "pUS3 has been further demonstrated to affect T cell activity and interferon signaling followed by impaired immune responses against viral infection resulting in longer survival times." (PMID 32226043, 2020). "pUS3 is a multifunctional protein which is involved in different processes during viral infection." (PMID 32226043, 2020). "However, we note reduced abundance of viral proteins in HaCaT cells infected with ΔpUS3 HSV-1, presumably due to restricted virus infection caused by an absence of pUS3-mediated innate immune evasion." (PMID 34398933, 2021). "Viral infection affected host factors that regulate pseudouridine modification, downregulating DKC1 (also called Cbf5), PUS1, PUS3, and RPUSD2 (also called PUS9), as shown in one of six transcriptome experiments, each." (PMID 34502037, 2021).
breast carcinoma (1 paper, 2026). "While higher expression of PUS4 was associated with more favorable prognosis, higher expression of PUS1, PUS3, and PUS7 in breast cancer patients was correlated with poorer prognosis." (PMID 41554761, 2026). "The mRNA levels of key PUS family members, i.e., PUS1, PUS3, PUS4, and PUS7, were significantly higher in breast cancer patient tissues compared with normal breast tissues." (PMID 41554761, 2026).
Cerebellar hypoplasia (1 paper, 2022). Cerebellar hypoplasia is a descriptive term implying a cerebellum with a reduced volume, but a normal shape and is stable over time. "Recently, a large exome sequencing study of children and adults with DWM and cerebellar hypoplasia expanded the list of genes associated with DWM to include TUBA1A, BRAF, SETD2, FOXP1, PUS3, ARMC9, and PIBF1." (PMID 35202430, 2022).
lung carcinoma (1 paper, 2024). "In lung cancer (LUAD, LUSC), DKC1, PUS1, PUS3, PUS7, TRUB1, and TRUB2 expression was mostly negatively correlated with immune cell infiltration." (PMID 39162904, 2024).
meningoencephalitis (1 paper, 2020). Inflammation of the meninges and brain, generally secondary to an infectious cause. "In summary, mice infected with PrV lacking pUL21 and functional pUS3 kinase were able to survive infection despite extensive neuroinvasion and severe meningoencephalitis." (PMID 32226043, 2020).
Sepsis (1 paper, 2023). Sepsis is defined as life-threatening organ dysfunction caused by a dysregulated host response to infection. "Finally, by using machine learning, we identified five hub RMGs (NSUN7, FTO, NOP2, PUS1, and PUS3), which showed efficient diagnostic value of sepsis." (PMID 37701433, 2023). "Overall, NSUN7, NOP2, PUS1, PUS3, and FTO were identified as important diagnostic markers for sepsis." (PMID 37701433, 2023). "Firstly, we determined the genes expression in PBMCs by qRT-PCR analysis, and found the expression of NSUN7, NOP2, PUS1 and PUS3 in septic patients (septic shock and sepsis) at day 1 were significantly higher than in healthy volunteers, and FTO expression was lower in septic patients." (PMID 37701433, 2023). "To predict the occurrence of sepsis, we constructed a nomogram model for diagnosing sepsis based on the expression levels of five hub RMGs (NSUN7, FTO, NOP2, PUS1 and PUS3)." (PMID 37701433, 2023). "In addition, we identified that five RMGs (NSUN7, NOP2, PUS1, PUS3 and FTO) could function as biomarkers for clinic diagnose of sepsis." (PMID 37701433, 2023).
infection (9 papers, 2012 to 2025). The state of being infected such as from the introduction of a foreign agent such as serum, vaccine, antigenic substance or organism. "While infection with ΔpUL21 HSV-1 causes a dramatic increase in the abundance of multiple phosphorylated pUS3 substrates, the abundance of these phosphoforms is indistinguishable between WT and pUL21V382E HSV-1." (PMID 36243114, 2022). "The peak of pUL21 expression is at late times (18 h) post-infection in cultured keratinocytes, whereas pUS3 abundance peaks at 6 h post-infection and then declines slightly." (PMID 41237910, 2025). "Others are known or suggested to modulate nuclear functions throughout the infection cycle, for example, pUL13 and pUS3." (PMID 30548142, 2019). "For PRV, group A p21-activated kinases (PAKs) were found to be involved in the pUS3-induced modulation of the actin cytoskeleton and the migration of virus particles through cell projections, ultimately leading to infection of neighboring cells." (PMID 27754319, 2016). "We hypothesize that the PP1-binding motif of pUL21 is specifically tuned to prevent effective PP1 binding at early times post-infection, when pUS3 activity is presumably pro-viral." (PMID 41237910, 2025). "One could thus hypothesise that pUL21 confers temporal regulation of pUS3-dependent protein phosphorylation, promoting dephosphorylation of specific pUS3 substrates at late times post-infection to ensure coordinated progression of virus replication." (PMID 34398933, 2021). "In contrast to pUS3, which is expressed immediately after infection and plateaus at around 6 hours post-infection (hpi), pUL21 is a late gene and its abundance increases steadily as the infection progresses." (PMID 34398933, 2021). "The abundance of pUL31 is particularly diminished in the ΔpUS3 infection, suggesting that pUS3 may be required for pUL31 stability in HaCaT cells." (PMID 34398933, 2021). "After intranasal inoculation with a PrV mutant lacking tegument protein pUL21 and pUS3 kinase activity (PrV-ΔUL21/US3Δkin), nearly all mice survived despite extensive infection of the central nervous system." (PMID 32226043, 2020).
tumor (4 papers, 2023 to 2026). "Among them, PUS7 and PUS3 showed the strongest correlations with tumour‐promoting phenotypes, with high PUS7 expression in PDAC predicting poor overall survival." (PMID 41496500, 2026). "Strikingly, patients exhibiting elevated levels of PUS1, PUS3, PUSL1, RPUSD1-4, and TRUB2 demonstrated a significantly shorter disease-free survival, as evidenced by combined analysis with tumor disease-free survival data." (PMID 39247811, 2024). "We initially calculated the univariate and multivariate analysis of overall survival (OS) rate, including the expression of genes belonging to the PUS family (PUS1, PUS3, PUS7, PUS10, PUS7L, PUSL1), patients’ age, gender, race and Tumor Node Metastasis (TNM)-stage, and set grade as co-variate." (PMID 37315299, 2023). "The most affected tumor type was PRAD, in which the expression of five synthases, DKC1, PUS3, RPUSD4, PUS7, and TRUB2, had mostly negative effects on DSS." (PMID 39162904, 2024).
cancer (3 papers, 2022 to 2026). A tumor composed of atypical neoplastic, often pleomorphic cells that invade other tissues. "RPUSD1 exhibited markedly elevated expression across pan‐cancer tissues, followed by TRUB2, TRUB1, and PUS3." (PMID 41496500, 2026).
PUS3 also shares sentences with these, for which no sentence is quoted: acute coronary syndrome (1 paper); brain disorder (1); Cirrhosis (1); developmental delays (1); heart failure (1); laryngeal squamous cell carcinoma (1); liver cancer (1); neurodegenerative disease (1); neuropathies (1); non-small cell lung carcinoma (1); prostate adenocarcinoma (1); prostate carcinoma (1); psychosis (1); schizophrenia (1); sclerosing cholangitis (1); septic shock (1); thyroid cancer (1).